GNA12 (G protein subunit alpha 12)
Diseases named in the same sentence as GNA12 in open-access papers:
GNA12 is named in the same sentence as 47 diseases in open-access papers, as found by Europe PMC text mining. Sharing a sentence is not in itself a finding about the gene and the disease. The quoted sentences say what the papers report.
breast carcinoma (9 papers, 2016 to 2024). "In addition to studies linking G12-associated processes with tumorigenesis, GNA12 signaling induces a striking increase in cancer cell invasion in vitro, and inhibition of GNA12 signaling significantly reduces breast cancer metastasis in vivo." (PMID 28394299, 2017). "Activated GNA12 also promotes prostate and breast cancer cell invasion in vitro and in vivo, and its expression is up-regulated in many tumors, particularly metastatic tissues." (PMID 28394299, 2017). "GNA12 is an α guanine nucleotide-binding protein, and these heterotrimeric subunits link GPCRs to the nucleotide exchange factors, which interact with Rho GTPases that regulate cell invasion in breast cancer (Chia, Kumari & Casey, 2014)." (PMID 36452073, 2022). "Our findings suggest that miR-564 is a potential tumor suppressor that regulates both PI3K and MAPK signaling by directly targeting a network of genes (AKT2, GNA12, GYS1 and SRF) linked to these pathways, and thus controls breast cancer cells proliferation, EMT, migration and invasion." (PMID 27600857, 2016). "Our present study demonstrates a distinct regulatory role of miR-564 in breast cancer progression by direct targeting of a network of genes, namely AKT2, GNA12, GYS1 and SRF that leads to simultaneous inhibition of PI3K and MAPK pathways." (PMID 27600857, 2016). "In conclusion, combined analyses of AKT2, GNA12, GYS1 and SRF expression mimic the effects of miR-564 on tumor progression and survival of breast cancer patients." (PMID 27600857, 2016). "In addition, the other three host genes (GNA12, BTRC, and MS4A7) correlated to lncRNA expression have been demonstrated to be associated with cancer progression, and specifically, the enhancement of BTRC expression could facilitate M2 macrophage polarization in breast cancer." (PMID 39126025, 2024).
depression (3 papers, 2010 to 2025). "Among the cognate genes, six including ALG8, DGKE, GNA12, KLF11, LRPAP1, and MMAB are related to multiple genetic diseases such as depressive disorder and Type-II diabetes." (PMID 22348086, 2012). "The jointly up-regulated expression of both the phospholipases and GNA12 and GNA13 suggests a relationship between glioblastoma, inflammation, and depression." (PMID 20122237, 2010).
head and neck squamous cell carcinoma (3 papers, 2022 to 2024). A squamous cell carcinoma that arises from any of the following anatomic sites: lip and oral cavity, nasal cavity, paranasal sinuses, pharynx, larynx, and salivary glands. "As such, GNA12 and GNA13 have been shown to be overexpressed in multiple tumor types such as liver, gastric, head and neck squamous cell carcinomas among others." (PMID 38965558, 2024). "The results of Gene Expression Omnibus and The Cancer Genome Atlas database analysis have shown that GNA12 can be used as a biomarker for the personalized treatment of head and neck squamous cell carcinoma (HNSCC) patients and one of the prognostic genes for patients with HNSCC." (PMID 35237598, 2022).
inflammatory bowel disease (3 papers, 2021 to 2023). A spectrum of small and large bowel inflammatory diseases of unknown etiology. "Gna12 has been identified as one of the reported inflammatory bowel disease (IBD) susceptibility genes in genome-wide association studies (GWAS)." (PMID 37426201, 2023). "As for GNA12, it was identified as an important signature involved in pathways in inflammatory bowel diseases and prostate cancer." (PMID 34150627, 2021).
prostate carcinoma (3 papers, 2015 to 2021). A carcinoma that arises from epithelial cells of the prostate gland. "Taken together, our data clearly indicate that c-Jun is an important control element for GNA12 expression in prostate cancer cells, and confirm a critical role for GNA12 in PC3 cell invasion." (PMID 28394299, 2017). "The poorly-aggressive prostate cancer cell line, LnCAP (low metastatic prostate cancer cells), showed much lower levels of GNA12 protein than the much more aggressive PC3 line." (PMID 28394299, 2017). "To explore the mechanism of GNA12 up-regulation in cancers, we chose to start with well-characterized prostate cancer cell lines." (PMID 28394299, 2017). "Several studies have reported that GNA12 levels are highly up-regulated in cancers, with prostate cancer being among the first reported." (PMID 28394299, 2017). "The current study suggest things are different for GNA12 and that, at least in the case of prostate cancer cells, the major point of control is at the transcriptional level." (PMID 28394299, 2017). "On the other hand, expression of Gα12-QL (a dominant active mutant of GNA12) in breast and prostate cancer cells has been shown to induce in vitro invasion and metastatic spread in mice." (PMID 25889182, 2015). "Further, blockade of GNA12/13 signaling using the specific inhibitor p115RGS has been shown to inhibit breast and prostate cancer metastasis both in vitro and in vivo." (PMID 25889182, 2015). "In this study, we explored the control of expression of GNA12 in prostate cancer cells." (PMID 28394299, 2017). "GNA12-5′ regulatory region reporter activity also paralleled the mRNA and protein levels, and dissection of the 5′ regulatory region led to the identification of c-Jun as directly targeting the element and as a positive regulator of GNA12 transcription in prostate cancer cells." (PMID 28394299, 2017). "Additionally, examination of the panel of prostate cancer cells from low metastatic to high metastatic (LnCap, DU145, PC3) showed parallel levels of c-Jun and GNA12; i.e., c-Jun level correlated with GNA12 level in the three cell lines." (PMID 28394299, 2017). "Silencing of c-Jun expression reduced mRNA and protein levels of GNA12, but not the closely-related GNA13, in prostate cancer cells." (PMID 28394299, 2017).
glioma (2 papers, 2023 to 2024). A benign or malignant brain and spinal cord tumor that arises from glial cells (astrocytes, oligodendrocytes, ependymal cells). "Two additional studies suggest that DUSP-4 may be a diagnostic and prognostic marker for IDH1 mutant gliomas, GNA12 signaling regulation promotes transcriptional and phenotypic responses to GBM tumor invasion." (PMID 39830513, 2024).
melanoma (2 papers, 2013 to 2015). A malignant, usually aggressive tumor composed of atypical, neoplastic melanocytes. "The important finding of this study is that mutation in the GNA12 gene can influence both the development of melanoma and the permeability of the BBB, and thereby contribute to the progression of melanoma to its metastatic state." (PMID 23641255, 2013). "In the context of melanoma, somatic splice-site mutation of TMEM216 suggests potential tumor suppressor function and sets the RHOA/GNA12 pathway apart from the Gs-protein/MAPK pathway by mutual exclusivity of TMEM216 towards known oncogenes NRAS and RAC1." (PMID 25600636, 2015). "The role of GNA12 is not limited to its involvement in melanoma and corresponding brain metastases." (PMID 23641255, 2013).
Obesity (2 papers, 2024 to 2025). Accumulation of substantial excess body fat. "In this study, the cg23627948 site was identified as mediating the impact of organophosphate and maternal lead exposure on obesity through the GNA12 gene, which is a member of the G protein-coupled receptor α family." (PMID 39189255, 2024).
oral cancer (2 papers, 2015 to 2025). "Overexpression of this protein drives migration and invasion of oral cancer cells; targeting of GNA12 was proposed for prevention of metastasis." (PMID 26179909, 2015).
ovarian carcinoma (2 papers, 2014 to 2024). A malignant neoplasm originating from the surface ovarian epithelium. "Transcriptomic analysis of SKOV3 ovarian cancer cells treated with LPA indicated that GNA12 drives the decreased expression of ATG16L1, a protein involved in autophagosome formation." (PMID 39513923, 2024). "Defining these pathways has shown that the gep protooncogene GNA12 is specifically involved in the proliferation of ovarian cancer cells whereas GNA13 is involved in cancer cell metastasis." (PMID 24940381, 2014). "In ovarian cancer, LPA acts as an autocrine stimulator of cell proliferation and cell migration by interacting with LPA receptors, mainly via the G12 protein α subunit encoded by the oncogene GNA12." (PMID 39513923, 2024).
pancreatic adenocarcinoma (2 papers, 2019 to 2022). "GNA12 has been shown to be involved in human pancreatic adenocarcinoma cell migration, hepatocarcinoma progression, and oral squamous cell carcinoma invasion, and may play a role in the pathogenesis of pre-eclampsia." (PMID 30530863, 2019).
pancreatic cancer (2 papers, 2021 to 2023). "For example, GNA12 together with GNA13 promotes gastrin-induced directional migration of pancreatic cancer cells via the cholecystokinin B receptor-GNA12/13-RhoA-ROCK signaling pathway." (PMID 37426201, 2023).
schizophrenia (2 papers, 2012 to 2025). A major psychotic disorder characterized by abnormalities in the perception or expression of reality. "About half of them has been previously associated with schizophrenia in humans, such as Olig1, Fgfr1, Gpr17, Gna12, Abca2, Sox1, Dpm2, and, as a locus for de novo mutations, Rab2a." (PMID 39825014, 2025). "An RNA sequencing analysis of the PFC suggested a dysregulation of numerous schizophrenia related genes including Olig1, Fgfr1, Gpr17, Gna12, Abca2, Sox1, Dpm2, and Rab2a in the rat model of psychosis." (PMID 39825014, 2025).
ulcerative colitis (2 papers, 2014 to 2017). An inflammatory bowel disease involving the mucosal surface of the large intestine and rectum. "For example, GNA12 has been demonstrated to play a key role in barrier function in the development of ulcerative colitis." (PMID 25544849, 2014).
asthma (1 paper, 2015). "Evidence from both methods implicated sphingolipid metabolism; in particular, the BN subnetwork of GNA12, PRKCE and S1P, may represent a potential mechanism for asthma control." (PMID 26421150, 2015).
colitis (1 paper, 2023). Inflammation of the colon. "Whether GNA12 in intestinal macrophages affects the development of colitis through regulating C5a-induced cell migration remains to be explored." (PMID 37426201, 2023).
gastric cancer (1 paper, 2017). A primary or metastatic malignant neoplasm involving the stomach. "A similar pattern of activity of the 5′ regulatory region reporter constructs was also observed in the gastric cancer cell lines MKN7 (which contain low GNA12 levels) and YCC18 (which contain high GNA12 level) (data not shown)." (PMID 28394299, 2017).
metabolic dysfunction-associated steatotic liver disease (1 paper, 2024). Metabolic dysfunction-associated steatotic liver disease (MASLD, formerly known as nonalcoholic fatty liver disease or NAFLD) is a type of liver disease that is not caused by alcohol. "Finally, we assessed hepatic gene expression levels of GNA12 and GNA13 using liver biopsy samples obtained from human subjects with metabolic dysfunction-associated steatotic liver disease (MASLD; n = 24)." (PMID 39557854, 2024).
nonalcoholic steatohepatitis (1 paper, 2024). "GNA12 levels were also shown to be lower in the liver of high-fat-diet-fed mice and in patients with steatosis and/or nonalcoholic steatohepatitis." (PMID 39189255, 2024).
renal carcinoma (1 paper, 2023). A carcinoma arising from the epithelium of the renal parenchyma or the renal pelvis. "LPA promotes the interaction of GNA12 and EFA6 through LPAR2 and activates the ADP-ribosylation factors 6-based pathway, consequently promoting the invasion of renal cancer cells." (PMID 37426201, 2023).
sarcopenia (1 paper, 2024). Progressive decline in muscle mass due to aging which results in decreased functional capacity of muscles. "We found that loss of MuSC quiescence following inactivation of Gna12-Gna13 results in depletion of the MuSC pool and is associated with enhanced sarcopenia during aging." (PMID 39009565, 2024). "Inactivation of Gna12-Gna13 or Rhoa but not of Gnaq-Gna11 completely abrogated MuSC quiescence, which depleted the MuSC pool and was associated with accelerated sarcopenia during aging." (PMID 39009565, 2024).
cancer (16 papers, 2014 to 2025). A tumor composed of atypical neoplastic, often pleomorphic cells that invade other tissues. "GNA12, encoding a guanine nucleotide-binding protein, has been reported to be involved in the phosphate signaling pathway and is upregulated in cancer cells and tumor tissues." (PMID 34787068, 2021). "Of note, there are more studies which focus on the role of GNA12 in cancer biology, while less was studied about the specific role of GNA13." (PMID 27883022, 2016). "Understanding the mechanisms by which GNA12 expression is upregulated in tumor progression may help in the development of drugs that target key elements responsible for metastasis and cancer progression." (PMID 28394299, 2017). "Most of the previous studies on the role of GNA12/13 in cancer have focused on GNA12." (PMID 25889182, 2015). "GNA12/13 proteins potentially mediate cancer cell invasion and metastasis by activating RhoA." (PMID 25889182, 2015). "Therefore, it is considered important to understand the control of GNA12 expression; such an understanding could shed light into its role in cancer." (PMID 28394299, 2017). "High expression of GNA12 was detected in OSCC patients and contributed to cancer cell migration and invasion and lymph node metastasis." (PMID 34576110, 2021). "Both GNA12 and GNA13 are known to be upregulated in aggressive cancer cells as well as advanced cancer tissues in several cancer types." (PMID 25889182, 2015). "Since most of the previous studies focused on GNA12, we have recently begun to assess the specific role(s) of GNA13 in cancer cell invasion, and the control of its expression in cancers." (PMID 25889182, 2015). "Analysis of cancer genomics databases show that GNA13 (but interestingly not GNA12) is indeed a strong prognostic marker for poor survival and metastasis in a range of solid tumors: head and neck, ovarian, lung and gastric." (PMID 29255247, 2018). "Additionally, analysis of expression profiles of the NCI-60 panel of cancer cell lines showed that GNA13 mRNA levels, but not GNA12, correlate significantly with the CSC/TIC marker ALDH1 (p = 0.037)." (PMID 29255247, 2018).
tumor (16 papers, 2015 to 2024). "GNA12 encodes for the G12 alpha subunit of G proteins and is of critical importance in regulating actin cytoskeletal remodeling in cells during migration, which is critical for tumor invasion." (PMID 36213002, 2022). "To further investigate the role of G⍺12 in GBM tumor invasion we examined the effect of GNA12 knockdown on GSC migration and invasion in vitro." (PMID 38104152, 2023). "GNA12 was notably upregulated in tumor samples largely distinct from those showing overexpression of these GPCRs." (PMID 38104152, 2023). "Their results also show that GNA12 stimulates the expression and activity of tumor promoting cytokines IL-6 and IL-8 and MMP-2 via binding and activation of NF-kB." (PMID 27551323, 2016). "Interestingly, the enhanced signaling of GNA12 that occurs during tumor progression appears to be due to enhanced expression of the protein rather than to mutational activation." (PMID 28394299, 2017). "Understanding the mechanisms by which GNA12 expression is controlled may aid in the development of therapies that target key elements responsible for GNA12-mediated tumor progression." (PMID 28394299, 2017). "Different Ga protein families have different functions in the occurrence and development of tumors, such as GNA12 and GNA13, which belong to the GNA12/13 family and play a role in promoting oncogenic transformation and tumor cell growth." (PMID 33500727, 2021). "Immunohistochemical analysis of the tissue micro array derived from these patients established the functional correlation between the decreased expression of tumor suppressive miRNAs and their target oncogenes: ERBB2, EGFR, EPHA2, BAX, GNA12, GNA13, and JUN." (PMID 28740575, 2017).
infection (1 paper, 2026). The state of being infected such as from the introduction of a foreign agent such as serum, vaccine, antigenic substance or organism. "Despite inter-individual variability and cohort heterogeneity, our findings regarding four DMPs (IFI44L, MX1, DDX60, and RABGAP1L) and two DMRs (PARP9 and GNA12) replicate changes described both in the acute phase of infection and at long-term follow-up." (PMID 42288901, 2026).
GNA12 also shares sentences with these, for which no sentence is quoted: glioblastoma (3 papers); Type-II diabetes (2); Alzheimer disease (1); bladder cancer (1); congenital disorder of glycosylation (1); coronary artery disease (1); dengue (1); dyslipidemia (1); esophageal carcinoma (1); esophageal squamous cell carcinoma (1); genetic diseases (1); Hypertension (1); Insulin resistance (1); liver cancer (1); oral squamous cell carcinoma (1); preeclampsia (1); prostate adenocarcinoma (1); psoriasis (1); psychosis (1); skin cutaneous melanoma (1); Splenomegaly (1); steatosis (1); thymoma (1).